ATP1A1 (ATPase Na+/K+ transporting subunit alpha 1)
Diseases named in the same sentence as ATP1A1 in open-access papers (continued):
Sharing a sentence is not in itself a finding about the gene and the disease.
infection (continued). "Consistent with the ATP1A1 knockdown, a significant reduction in Tyr845 phosphorylation also was observed when the cells were pre-treated with ouabain, PST2238, or Src-kinase inhibitors (SrcI-I +PP2) prior to infection with RSV." (PMID 31381610, 2019). "In addition, we attempted to overexpress ATP1A1 protein on PTR2 and DF-1 cells which could not support the infection of PEDV." (PMID 36835408, 2023).
peripheral neuropathy (3 papers, 2021 to 2025). A disorder affecting the peripheral nervous system. "Our results further confirm the causative role of ATP1A1 in peripheral neuropathy and broaden the mutational and phenotypic spectrum of ATP1A1-associated CMT." (PMID 36738336, 2023). "Pathogenic variants in ATP1A1 (ATPase Na+/K+ Transporting Subunit Alpha 1) were previously associated with peripheral neuropathy." (PMID 36738336, 2023). "These mutations were mainly concentrated in the topological regions of ATP1A1 (88.9%, 8/9), and one (11.1%, 1/9) located at the transmembrane region, suggesting that topological regions may have a specificity for peripheral neuropathy." (PMID 33968856, 2021).
adenocarcinoma (1 paper, 2024). A common cancer characterized by the presence of malignant glandular cells. "To investigate the role of the Na,K-ATPase α1 subunit (ATP1A1), which is the subunit that binds to Ouabain, we examined its expression in healthy colon tissue and adenocarcinoma by using its expression data available in the Human Protein Atlas." (PMID 38713004, 2024). "ATP1A1 mRNA expression was analyzed in 373 normal colon tissues and 596 adenocarcinoma samples." (PMID 38713004, 2024).
brain disease (1 paper, 2015). "Moreover, 10 genes (ATP1A1, ATP6V1D, C16orf45, CROCC, KLC1, LUC7L2, PIAS2, PRKAR1B, RBFOX1, and RPL19) interacts with at least one brain disease-associated gene." (PMID 26043779, 2015). "As the result, the three genes (ATP1A1 for BD, RBFOX1 for BD, and KLC1 for AD and PD) are directly related to brain diseases." (PMID 26043779, 2015).
genetic diseases (1 paper, 2021). "In summary, two novel de novo ATP1A1 variants were identified in two cases in this study, enriching the phenotypic spectrum of ATP1A1 mutation-related genetic diseases." (PMID 33968856, 2021).
neurodegenerative disease (1 paper, 2023). A disorder of the central nervous system characterized by gradual and progressive loss of neural tissue and neurologic function. "Second, while dysfunctions in ubiquitous ATP1A1 and neuron-specific ATP1A3 have been predominantly linked to neurodevelopmental disorders, their role in regulating miR-132 may suggest potential underexplored functions in neurodegenerative diseases." (PMID 37989753, 2023).
psychiatric disorder (1 paper, 2021). A disorder characterized by behavioral and/or psychological abnormalities, often accompanied by physical symptoms. "Two of the other top DMP-associated genes, ATP1A1 and ZNF323, were also involved in psychiatric disorders and neural function." (PMID 34938161, 2021).
ATP1A1 also shares sentences with these, for which no sentence is quoted: esophageal squamous cell carcinoma (4 papers); mastitis (4); Hypertension (3); sleep disorder (3); Spastic paraplegia (3); adrenal tumor (2); Ataxia (2); colitis (2); developmental delay (2); neuroblastoma (2); neurodevelopmental disorder (2); sarcoma (2); type 2 diabetes (2); adrenocortical tumors (1); Areflexia (1); astrocytomas (1); atherosclerosis (1); autism spectrum disorder (1); Bartter syndrome type 3 (1); Bartter syndrome type 4 (1); Burkitt lymphoma (1); cardiovascular disease (1); cerebellar ataxia (1); cholangiocarcinoma (1); colon adenocarcinoma (1); deafness (1); Dupuytren’s Disease (1); Epileptic encephalopathy (1); escherichia coli infection (1); familial hemiplegic migraine type 2 (1).
A further 22 diseases each share a sentence with ATP1A1 in 1 paper.